CKMT2 (creatine kinase, mitochondrial 2)
Description:
Reversibly catalyzes the transfer of phosphate between ATP and various phosphogens (e.g. creatine phosphate). Creatine kinase isoenzymes play a central role in energy transduction in tissues with large, fluctuating energy demands, such as skeletal muscle, heart, brain and spermatozoa.
Synonyms: SMTCK
Tractability: Small molecule: a structure with a bound ligand is known; it has a high-quality binding pocket. Antibody: UniProt places it where antibodies can reach, with medium confidence.
Gene: Protein-coding gene on chromosome 5 (81,233,320 to 81,266,399, forward strand). Ensembl gene ENSG00000131730.
Subcellular location: Mitochondrion inner membrane
Pathways (Reactome):
Metabolism: Creatine metabolism
Gene Ontology:
Molecular function: protein binding; creatine kinase activity; catalytic activity; kinase activity; phosphotransferase activity, nitrogenous group as acceptor; transferase activity, transferring phosphorus-containing groups
Biological process: muscle contraction; phosphocreatine biosynthetic process
Cellular component: mitochondrion; mitochondrial inner membrane
Genetic constraint (gnomAD): Loss-of-function variants: 32 observed, 40.28 expected, observed/expected ratio (o/e) 0.79, 90% interval 0.6 to 1.07. The upper end of that interval is the gene's LOEUF score, 1.07, which puts it in group 4 of 6, group 1 being the genes least tolerant of losing a copy. Missense variants: 421 observed, 517.3 expected, observed/expected ratio (o/e) 0.81, 90% interval 0.75 to 0.88. Synonymous variants: 187 observed, 204.12 expected, observed/expected ratio (o/e) 0.92, 90% interval 0.81 to 1.03.
Homologues: Orthologues: chimpanzee CKMT2 (100% identical), macaque CKMT2 (99% identical), rabbit CKMT2 (97% identical), dog CKMT2 (97% identical), mouse Ckmt2 (96% identical), rat Ckmt2 (96% identical), guinea pig CKMT2 (95% identical), pig CKMT2 (95% identical), zebrafish ckmt2a (79% identical), zebrafish ckmt2b (78% identical), Drosophila melanogaster Argk1 (36% identical), Caenorhabditis elegans F46H5.3 (35% identical), and 7 more. Paralogues in human: CKMT1A (79% identical), CKMT1B (79% identical), CKB (58% identical), CKM (57% identical).
Diseases named in the same sentence as CKMT2 in open-access papers:
CKMT2 is named in the same sentence as 29 diseases in open-access papers, as found by Europe PMC text mining. Sharing a sentence is not in itself a finding about the gene and the disease. The quoted sentences say what the papers report.
osteosarcoma (7 papers, 2020 to 2026). A usually aggressive malignant bone-forming mesenchymal neoplasm, predominantly affecting adolescents and young adults. "While previous studies have associated CKMT2 expression with malignancies such as osteosarcoma and gastric cancer, there are few reports on the biological functions and molecular mechanisms underlying CKMT2 in tumors." (PMID 38952967, 2024). "CKMT2 was selected as a hypoxia-immune-related microenvironment prognostic gene for osteosarcoma as a risk gene, which is consistent with our result." (PMID 38039294, 2023). "A risk model composing of ZYX, GJA5, GAL, GRAMD1B, and CKMT2 was established for assessing osteosarcoma prognosis." (PMID 38039294, 2023). "CKMT2 is linked to gastric cancer prognosis and osteosarcoma progression." (PMID 38104097, 2023). "CKMT2 is established as a key driver of osteosarcoma progression, serving both as a prognostic biomarker and a potential therapeutic target." (PMID 42272640, 2026). "CKMT2 is a key regulatory factor in the occurrence and development of osteosarcoma and is significantly related to OS in patients." (PMID 38172162, 2024). "It was concluded that CKMT2 was a key regulatory factor in the development of osteosarcoma, and significantly correlated with patient OS." (PMID 32920549, 2020). "Considering the heterogeneity between molecular subtypes defined by specific oxidative stress genes, we identified the DEGs between the two molecular subtypes and deduced a risk assessment system composing of ZYX, GJA5, GAL, GRAMD1B, and CKMT2 for the prognosis of osteosarcoma." (PMID 38039294, 2023). "The expression of BNIP3, SLC38A5, CKMT2, CXCL11, SLC5A3, S100A3, and PGM1 genes was verified in osteosarcoma cells (Saos-2 and 143B) and normal osteoblasts (hFOB1.19)." (PMID 36578780, 2022).
colon cancer (3 papers, 2022 to 2024). "The expression of CKMT2 was up-regulated (P < 0.05) in human colon cancer cells (SW480, RKO) compared to human normal colon cells (FHC)." (PMID 38172162, 2024). "Immunohistochemical assays showed overexpression of CKMT2 in colon cancer and rectal cancer." (PMID 38172162, 2024). "Human normal colon cells (FHC) and four human colon cancer cells (SW480, RKO) were also selected to detect the mRNA expression of the CKMT2 at the cellular level." (PMID 38172162, 2024). "GGH, CACNG4, MME, SLC30A2, CKMT2, SYN3, and SLC22A31 were identified as differentially expressed both in glycolytic-cholesterogenic subgroups as well as between colon cancers and healthy samples, and were involved in glycolysis‒cholesterol synthesis." (PMID 36569910, 2022).
gastric cancer (2 papers, 2023 to 2024). A primary or metastatic malignant neoplasm involving the stomach. "Recently, a potential association between CKMT2 and metabolic dysregulation in gastric cancer has also been suggested." (PMID 38952967, 2024).
ischemia (2 papers, 2023 to 2024). A hypoperfusion of the BLOOD through an organ or tissue caused by a PATHOLOGIC CONSTRICTION or obstruction of its BLOOD VESSELS, or an absence of BLOOD CIRCULATION. "In the intact rabbit heart, a rapid and irreversible loss of CKMT2 was observed, which was directly related to the duration of ischemia." (PMID 39045601, 2024). "Mitochondrial creatine kinase S-type (CKMT2) was among the proteins that were phosphorylated during IPC with the tyrosine Y368 site phosphorylated in IPC and perfusion samples, and dephosphorylated in ischemia only and I/R samples." (PMID 36902123, 2023).
Obesity (2 papers, 2021 to 2023). Accumulation of substantial excess body fat. "A total of 175 genes including thermogenic markers (UCP2, CKMT2, and CITED1) and 5 BATLAS markers (PPARGC1B, ACO2, ACSF2, NNAT, and DMRT2) were expressed less in active beige adipocytes carrying FTO obesity-risk variant as compared to risk-free carriers." (PMID 37416800, 2023). "Due to high species conservation, the identified genes related to human or mice obesity traits may hold importance for adipose deposition in chickens, such as ELOVL7, IL6ST, IQGAP2, PAX5 and CKMT2." (PMID 34058970, 2021).
prostate carcinoma (2 papers, 2023 to 2024). A carcinoma that arises from epithelial cells of the prostate gland. "CKMT2 overexpression was positively correlated with the prognosis of lung adenocarcinoma and prostate cancer." (PMID 38172162, 2024).
acute myocardial infarction (1 paper, 2024). Necrosis of the myocardium, as a result of interruption of the blood supply to the area. "We identified Ckmt2 as a novel marker of reperfused but not non-reperfused AMI, correlating with infarct size and impaired cardiac function, highlighting its potential as a biomarker for reperfusion injury in acute myocardial infarction." (PMID 39457679, 2024).
asthma (1 paper, 2021). "The underlying key genes in asthma pathogenesis and those regulated by treatment including Adipoq, HMOX1, SPP1, Cyp2e1, TNC, MB, MPO, Col9a1, Ckmt2, and Erbb4 were taken as examples to illustrate the positions and relationships with other points and midline in the figure." (PMID 33531915, 2021).
COVID-19 (1 paper, 2022). A disease caused by infection with severe acute respiratory syndrome coronavirus 2. "The overexpression of CKM and CKMT2 in the s-WAT of infected patients was transient, declining two months after COVID-19 diagnosis and correlating with the final recovery after surgical interventions." (PMID 35455962, 2022). "Among them, CKMT2 and CKM stood out, and CKM increased for up to 60 days after the COVID-19 diagnosis." (PMID 35455962, 2022).
dilated cardiomyopathy (1 paper, 2025). Cardiomyopathy which is characterized by dilation and contractile dysfunction of the left and right ventricles. "In addition, upregulation of Kcna4 and downregulation of Ckmt2, genes linked to dilated cardiomyopathy and arrhythmia, have been observed in cardiac-specific MBNL1 and MBNL2 double-knockout mice and were also misregulated in CUG960 +dox mice." (PMID 39932794, 2025).
head and neck squamous cell carcinoma (1 paper, 2017). A squamous cell carcinoma that arises from any of the following anatomic sites: lip and oral cavity, nasal cavity, paranasal sinuses, pharynx, larynx, and salivary glands. "Furthermore, TNNC, CKMT2 and NEB1 turned out to be slightly under-express in head and neck squamous cell carcinoma with respect to normal tissue (E-GEOD-6631; log2FC=-1.3, −1.3 and −1, respectively, p-values <0.05)." (PMID 29285222, 2017).
left ventricular hypertrophy (1 paper, 2013). Enlargement of the LEFT VENTRICLE of the heart. "One exception is homozygous deletion of sarcomeric mitochondrial creatine kinase (Ckmt2) where hypotension, left ventricular hypertrophy and high cardiac output can occur depending on genetic background." (PMID 23874215, 2013).
mucinous carcinoma (1 paper, 2024). "CKMT2 expression level is higher in patients with adenocarcinoma patients compared with mucinous carcinoma (t = 2.169, p = 0.031)." (PMID 38952967, 2024).
myocarditis (1 paper, 2025). Myocarditis is a condition that is characterized by inflammation of the heart muscle (myocardium). "Using multiplexed TCR-MAP screens against our mouse proteome library, we were able to rapidly identify cardiac self-reactivity against CKMT2 for an expanded TCR clonotype derived from a mouse model of myocarditis." (PMID 38956325, 2025). "The reactivity of TCR4 against CKMT2 strongly suggests that this clonotype contributes to the pathology of myocarditis through recognition of self-antigens expressed in cardiac tissue." (PMID 38956325, 2025). "It will be interesting to assess whether CKMT2 also serves as an autoantigen for expanded CD8 TCRs in human patients with myocarditis." (PMID 38956325, 2025).
rectal cancer (1 paper, 2024). A primary or metastatic malignant neoplasm that affects the rectum. "Secondly, this study verified the expression of CKMT2 in colon and rectal cancer only at the protein level." (PMID 38172162, 2024).
renal cell carcinoma (1 paper, 2024). "Interestingly, high expressions of Myo18b, Ckmt2, and Eef1a2 showed unfavorable prognoses in H&N cancer, and Sln (sarcolipin) and Tceal7 are unfavorable for renal cell carcinoma." (PMID 38686626, 2024).
tumor (6 papers, 2020 to 2026). "The expression of CKMT2 is correlated with pathological types, tumor size, distant metastasis, and survival in CRC patients." (PMID 38952967, 2024). "Furthermore, patients with a tumor size ≥5 cm exhibited enhanced CKMT2 expression compared to their counterparts with a tumor size <5 cm (t = 2.294, p = 0.023)." (PMID 38952967, 2024). "The role of CKMT2 in tumor cell energy metabolism requires further research." (PMID 38952967, 2024). "Notably, the expression of the creatine kinase genes Ckm and Ckmt2 and the muscle‐specific glycolytic enzyme Eno3 was also reduced, implicating that the energy metabolism supporting muscle contraction was negatively impacted by tumours." (PMID 39001644, 2024). "Firstly, using the relevant data of IHC in the HPA database, the key genes CDKN2A, MSLN, and CKMT2 were compared at the protein level, and it was found that CDKN2A and MSLN were significantly highly expressed in the tumor tissues (p < 0.001; p < 0.05), which was consistent with our prediction." (PMID 39519383, 2024). "Finally, tumours with high grade (III-IV) are characterized by MAOB gene overexpression and CKMT2 gene downregulation, both related to arginine and proline metabolism pathway." (PMID 31949199, 2020).
cancer (5 papers, 2022 to 2024). A tumor composed of atypical neoplastic, often pleomorphic cells that invade other tissues. "In this study, we demonstrated that CKMT2 expression is associated with TMB in 17 cancers and MSI in 6 cancers." (PMID 38172162, 2024). "The results showed that CKMT2 was strongly associated with most immune-related genes in specific cancer types, such as ACC, BLCA, BRCA, KIRC, LUAD, PRAD, and THCA." (PMID 38172162, 2024). "The cBioPortal database was used to evaluate the frequency of CKMT2 changes and mutation counts in cancer patients." (PMID 38172162, 2024). "The abnormal expression of CKMT2 is associated with poor prognosis of many types of cancer and with immune infiltration in TME, especially with TAM." (PMID 38172162, 2024). "The association between CKMT2 expression and cancer survival outcomes was investigated using both one-way Cox and KM analyses for OS, DSS, DFI, and PFI." (PMID 38172162, 2024). "To study the relationship between immune cell infiltration and CKMT2 expression at the pan-cancer level, we downloaded immune cell infiltration data from the database for correlation analysis." (PMID 38172162, 2024). "The results showed that compared with paracancerous tissues and normal tissues, CKMT2 gene mRNA was overexpressed in CKMT2 in 4 kinds of cancers." (PMID 38172162, 2024). "Seven cancers were positively correlated with low CKMT2 expression in tumor microenvironment analysis." (PMID 38172162, 2024). "Using the TCGA cohort, the expression of CKMT2 was positively correlated with the immune score of 7 cancers and negatively correlated with the immune score of 8 cancers." (PMID 38172162, 2024). "COAD was selected from four cancers overexpressing CKMT2 for CKMT2 gene expression analysis in the GEO database." (PMID 38172162, 2024). "We aimed to explore the prognostic value of CKMT2 in 33 cancer types and investigate its potential immune function." (PMID 38172162, 2024). "We first used TCGA data sets to evaluate the expression and prognostic significance of CKMT2 in pan-cancer." (PMID 38172162, 2024). "In this study, we analyzed the specific role and potential mechanisms of CKMT2 in a pan-cancer dataset." (PMID 38172162, 2024). "For further validation, an analysis of The Cancer Genome Atlas (TCGA) database, a widely acknowledged repository of cancer gene information, revealed a significant upregulation of CKMT2 mRNA in CRC tissues in contrast to normal controls (p < 0.001)." (PMID 38952967, 2024). "The results from the database show that CKMT2 is overexpressed in four of these cancers: CHOL, COAD, KICH, and READ." (PMID 38172162, 2024). "MHC gene is co-expressed with CKMT2 in almost all cancer types, especially in BLCA, CESC, KIRC, LUAD, and THCA." (PMID 38172162, 2024). "The staining intensity of CKMT2 in cancer tissues exhibited a robust pattern, contrasting with the minimal to absent staining observed in adjacent nontumor tissues." (PMID 38952967, 2024). "In contrast, low CKMT2 expression was observed in 14 cancers, and the IHC analysis of HPA was consistent with the expression of CKMT2 mRNA." (PMID 38172162, 2024). "CKMT2 plays an important role in tumorigenesis and cancer immunity and can be used as a prognostic biomarker and potential target for cancer immunotherapy." (PMID 38172162, 2024). "We carried out gene co-expression analysis to explore the relationship between CKMT2 expression and immune-related genes in different types of cancer." (PMID 38172162, 2024). "Relationship between CKMT2 immunohistochemical score in cancer tissues and clinical pathological features in 220 patients with colorectal cancer." (PMID 38952967, 2024). "Among the five cancers, low expression of CKMT2 resulted in better immunotherapy treatment outcomes." (PMID 38172162, 2024). "There was a strong correlation between CKMT2 and most immune-related genes in specific cancer types." (PMID 38172162, 2024).
cancer (continued). "On the one hand, we analyzed the relationship between CKMT2 expression and patient prognosis in 33 cancer types." (PMID 38172162, 2024). "Among all cancers, the frequency of CKMT2 change was the highest (10%) in patients with CESC, with "mutation and deep deletion" as the main type." (PMID 38172162, 2024). "Here, we analyzed the expression profile and prognostic value of CKMT2 in pan-cancer by bioinformatics and explored its potential role in tumor immunology." (PMID 38172162, 2024). "Next, we will supplement experiments to clarify the mechanisms of CKMT2 in different types of cancers at the cellular and molecular levels." (PMID 38172162, 2024). "Although CKMT2 expression is associated with immune cell infiltration and patient survival in cancer, we cannot confirm whether CKMT2 may affect patient survival through immune pathways." (PMID 38172162, 2024). "Therefore, CKMT2 can be used as a potential predictor of immunotherapy efficacy in these types of cancer." (PMID 38172162, 2024). "However, the high expression of CKMT2 is associated with a better prognosis in patients with PRAD, which means that the function of CKMT2 is more like a protective role in particular cancer." (PMID 38172162, 2024). "Similarly, we further found that the expression of CKMT2 was negatively correlated with MSI in six cancers, including COAD, HNSC, PAAD, STAD, and UCEC, and positively correlated with MSI only in LUAD." (PMID 38172162, 2024). "In addition, CKMT2 expression is associated with TMB and MSI in many cancer types, suggesting that CKMT2 is associated with current predictors of ICI efficacy." (PMID 38172162, 2024). "In addition, the expression of CKMT2 was positively correlated with the matrix score of 11 cancers and negatively correlated with 5 cancers." (PMID 38172162, 2024). "Beyond cardiovascular disease, investigating Ckmt2’s role in other mitochondria-related conditions, such as neurodegenerative diseases and certain cancers, may further broaden its relevance and inform future therapeutic strategies." (PMID 39457679, 2024). "In addition, immune activation genes and immunosuppressive genes are also closely related to the expression of CKMT2 in TCGA pan-cancer." (PMID 38172162, 2024). "We evaluated the relationship between each of them and the expression of CKMT2 in pan-cancer." (PMID 38172162, 2024). "The overexpression of CKMT2 has been reported in malignant tumors." (PMID 36578780, 2022). "However, no potential lncRNAs associated with CKMT2 in cancer have been reported." (PMID 38172162, 2024). "The correlation between CKMT2 expression and TMB was significant in all 17 kinds of cancer." (PMID 38172162, 2024). "Using qRT-PCR, the expression profile of CKMT2 was evaluated across human colonic epithelial cells (NCM460) and various human CRC cell lines (SW480, DLD-1, SW620, HCT116, HCT15), which are widely used in vitro cancer research." (PMID 38952967, 2024). "Notably, the immunohistochemical scoring indicated a marked elevation in the expression of CKMT2 in cancer tissues (1.60 ± 0.53) compared to adjacent nontumor tissues (0.45 ± 0.29), demonstrating statistical significance (t = 28.397, p < 0.001)." (PMID 38952967, 2024). "However, CKMT2 has not been widely studied in the field of cancer." (PMID 38172162, 2024).
infection (1 paper, 2022). The state of being infected such as from the introduction of a foreign agent such as serum, vaccine, antigenic substance or organism. "Altogether, our data suggest that the presence of CKMT2 or CKM in the s-WAT of SCI/PU post-COVID patients within six weeks after infection may represent a prognostic biomarker of poor postsurgical recovery." (PMID 35455962, 2022).
CKMT2 also shares sentences with these, for which no sentence is quoted: adenocarcinoma (1 paper); cardiovascular disease (1); colon adenocarcinoma (1); colorectal cancer (1); idiopathic dilated cardiomyopathy (1); lung adenocarcinoma (1); lymph node metastasis (1); neurodegenerative disease (1); rectum adenocarcinoma (1); thyroid carcinoma (1).